CAP2 (cyclase associated actin cytoskeleton regulatory protein 2)
Diseases named in the same sentence as CAP2 in open-access papers (continued):
Sharing a sentence is not in itself a finding about the gene and the disease.
glioma (continued). "Therefore, in the present study, the expression of CAP2 in gliomas compared to normal brain tissues was examined." (PMID 32042970, 2020). "Interestingly, analysis revealed that CAP2 gene was highly expressed in glioma tissues among the different datasets (fold change ranged between 1.044 and 3.352)." (PMID 32042970, 2020). "Statistical analysis indicated that CAP2 is an independent prognostic factor in gliomas." (PMID 32042970, 2020). "CAP2 overexpression was observed in 72% (30/42) of glioma tissues." (PMID 32042970, 2020). "This demonstrated that CAP2 might play an important role in the development and prognosis of gliomas." (PMID 32042970, 2020). "Hence, we were interested in investigating CAP2 expression in gliomas and evaluating its clinicopathological and prognostic significance." (PMID 32042970, 2020). "However, CAP2 positive staining was observed in 92.9% (39/42) of the glioma tissues." (PMID 32042970, 2020). "CAP2 expression level may serve as a promising target for diagnosis and treatment of glioma." (PMID 32042970, 2020). "Thus, we suggested that CAP2 might serve as a potential prognostic biomarker for gliomas." (PMID 32042970, 2020). "Nonetheless, and to the best of our knowledge, the status of CAP2 expression has not been addressed in gliomas yet." (PMID 32042970, 2020). "However, to date, the prognostic implication of CAP2 in gliomas has not been analyzed." (PMID 32042970, 2020). "One of the key regulators of the cellular actin dynamics is adenylyl cyclase-associated protein 2 (CAP2), a protein that has been studied before in the milieu of cancer and shown to be associated with tumor progression; yet, its expression levels in the context of gliomas have not been assessed." (PMID 32042970, 2020).
pancreatic cancer (2 papers, 2019 to 2023). "Considering that regulating the actin cytoskeleton is a key mechanism underlying the role of CAP1 in pancreatic cancer cell invasiveness, it is possible that CAP2 shares the role with CAP1 in regulating cancer cell invasiveness." (PMID 30894654, 2019). "The SLC22A3 and CAP2 might become specific predictive signatures for diagnosing pancreatic cancer." (PMID 37857015, 2023). "Through PPI construction, we identified several genes, including mRNA (CAP2, SLC22A3), miRNA (miR-9985, miR-27, miR-548), and TFs (CEBPA), involved in the prognosis mechanism of pancreatic cancer." (PMID 37857015, 2023).
Parkinson’s (2 papers, 2022 to 2024). "In the healthy and Parkinson’s groups, the expression of CAP2 gene in high-risk patients showed a significant down-regulation compared with low-risk patients." (PMID 38846945, 2024). "q-PCR results confirmed that mRNA CAP2 expression in the Parkinson’s group was lower than that in the healthy group, aligning with the earlier analysis." (PMID 38846945, 2024). "In addition, the results of the validation cohort showed that the expression of CAP2 in the Parkinson’s sample was downregulated compared to the normal sample." (PMID 38846945, 2024). "Interestingly, also in Parkinson’s disease patients, we found a selective reduction of CAP2 mRNA levels relative to controls but unaltered protein levels." (PMID 35163460, 2022). "Therefore, combined with our research, it can be inferred that CAP2 may affect Parkinson’s motor function limitation by affecting the connection between the long-term potentials and gaps of synapses, resulting in a series of related motor function changes such as bradykinesia, rigidity, and tremor." (PMID 38846945, 2024).
Ventricular arrhythmia (2 papers, 2015 to 2021). "Cap2-KO mice exhibit, DCM, ventricular arrhythmias and cardiac conduction problems." (PMID 33742108, 2021). "The CAP2 null mice also develop cardiac conduction disease and heart block prior to the onset of DCM, although they do not develop ventricular arrhythmias." (PMID 26616005, 2015).
atherosclerosis (1 paper, 2020). A disease characterized by the build-up of fatty material and calcium deposition in the arterial wall resulting in partial or complete occlusion of the arterial lumen. "As far as concern CAP1 and CAP2, potential roles have been described for various human pathologies apart from the already mentioned contributions of CAP1 to atherosclerosis or other cardiovascular diseases and of CAP2 to heart diseases and 6p22 syndrome." (PMID 33072768, 2020).
autosomal recessive cerebral atrophy (1 paper, 2015). "CAP2/Tmprss4 was found mutated in a new form of pediatric neurodegenerative disorder, termed Autosomal Recessive Cerebral Atrophy (ARCA), where a point mutation in the gene (c.995C>T) leads to severe CNS degeneration." (PMID 26309024, 2015).
bacteremia (1 paper, 2025). "Baseline characteristics were similar in this subset compared with the full Ubon-sepsis CAP cohort and etiologies of bacteremia showed similar separation between CAP1 and CAP2 in this subset." (PMID 41209652, 2025).
Bartter syndrome (1 paper, 2019). "CAP2/Tmprss4 might represent an interesting pharmacological target in diseases modulating diuresis, such as NDI or Bartter’s syndrome, especially in a context of low dietary potassium intake." (PMID 31863073, 2019).
Cachexia (1 paper, 2025). Severe weight loss, wasting of muscle, loss of appetite, and general debility related to a chronic disease. "Interestingly, muscles of B16F10-cachexia mice demonstrated a unique Cap2 EC subpopulation not present in control mice." (PMID 40419762, 2025).
cardiac conduction disease (1 paper, 2015). "A likely explanation for the differences observed in survival between cardiomyocyte-specific KO and whole body KO mice is that the loss of CAP2 in tissues other than the heart affects the secretion of factors, such as sex hormones, that can influence the progression of cardiac conduction disease." (PMID 26616005, 2015).
cognitive deficits (1 paper, 2023). "For instance, alterations in CAP2 pathway can contribute to synaptic dysfunction and cognitive deficits in AD patients and, thereby, CAP2 levels might be related to the neurocognitive component of frailty." (PMID 37537790, 2023).
colon cancer (1 paper, 2016). "To test the effects of CAP2 on the transcriptome we performed microarray analyses with human colon cancer Ls174T cells as these have been previously used to determine changes driven by dnTCF activity." (PMID 27973612, 2016). "Analyses in three colon cancer cell types revealed the epistatic rescue of the expression of AXIN2 from CAP2 repression in cells with TCFVP16." (PMID 27973612, 2016). "The ability of CAP2 to inhibit tumor growth was tested in immunocompromised NUDE mice xenografted with the TCF-dependent colon cancer cell line DLD1." (PMID 27973612, 2016). "Whereas there were small context-dependent differences, the canonical and bona fide colon cancer WNT-TCF targets AXIN2 and LGR5 were generally repressed at 5μM CAP2 (batch 2)." (PMID 27973612, 2016). "CAP2 repressed WNT-TCF targets in multiple cancer types including all colon cancer cell lines tested." (PMID 27973612, 2016). "Global analysis of HISTONE 3 marks reveal that CAP2, but not ivermectin, treatment of human colon cancer cells decreases overall H3K4me1 levels, supporting an effect of CAP2 on the epigenetic landscape, the reduction of a mark associated with active enhancers and the repression of associated genes." (PMID 27973612, 2016).
COVID-19 (1 paper, 2025). A disease caused by infection with severe acute respiratory syndrome coronavirus 2. "In the cohort of patients with COVID-19, CAP1 and CAP2 subphenotypes assigned by the PCM differed by key clinical characteristics and revealed an interaction between corticosteroid treatment and mortality (P = 0.002)." (PMID 41209652, 2025).
endothelial dysfunction (1 paper, 2025). In vascular diseases, endothelial dysfunction is a systemic pathological state of the endothelium (the inner lining of blood vessels) and can be broadly defined as an imbalance between vasodilating and vasoconstricting substances produced by (or acting on) the endothelium. "These scRNA-seq data indicate that the emergence of the unique Cap2 EC subpopulation may serve as a sentinel population for muscle endothelial dysfunction in cancer cachexia." (PMID 40419762, 2025).
influenza infections (1 paper, 2015). "While the physiological role of CAP2/Tmprss4 is largely unknown due to lack of a knockout model, CAP2/Tmprss4 was identified as involved in pathologies such as cancer, influenza infections and neurological disorders." (PMID 26309024, 2015).
lymph node metastasis (1 paper, 2023). "In this study, we demonstrated that cyclase-associated protein 2 (CAP2) was upregulated in GC, especially in cases with lymph node metastasis, and was correlated with a poorer prognosis." (PMID 37707957, 2023).
metastatic cancers (1 paper, 2019). A carcinoma which has spread from the original site of growth to another anatomic site. "Elevated expression of both human CAP isoforms (CAP1 and CAP2) is linked to poor prognosis in multiple different metastatic cancers." (PMID 31718088, 2019).
microphthalmia (1 paper, 2015). Congenital or developmental anomaly in which the eyeballs are abnormally small. "CAP2 knockout mice are also prone to eye infections, the underlying cause of which appeared to be microphthalmia." (PMID 26616005, 2015). "CAP2 knockouts are prone to eye infections, which are likely caused by microphthalmia." (PMID 26616005, 2015). "CAP2 knockouts resembled patients with 6p22 syndrome in that mice were smaller and they developed microphthalmia and cardiac disease." (PMID 26616005, 2015). "There is also a sex bias in other models of microphthalmia; however, in other models, microphthalmia is seen predominantly in females, while CAP2 knockouts predominantly show microphthalmia in males." (PMID 26616005, 2015).
nicotine addiction (1 paper, 2024). "CAP2 exhibited a positive correlation with endocrine and other factor-regulated calcium reabsorption, GABAergic synapse, glycosaminoglycan biosynthesis, nicotine addiction, and synaptic vesicle cycle." (PMID 38846945, 2024).
Obesity (1 paper, 2022). Accumulation of substantial excess body fat. "The cap2 cluster was increased in obesity and was enriched for lipid-processing pathways, such as PPAR signaling, fat digestion and absorption." (PMID 36400935, 2022).
oligodendroglioma (1 paper, 2012). A well-differentiated (WHO grade II), diffusely infiltrating neuroglial tumor, typically located in the cerebral hemispheres. "Three additional gene transcripts, CAP2, RELN and SIDT1, showed >20-fold increase in the level of latent splicing in Grade III oligodendroglioma compared to normal cells." (PMID 23002147, 2012).
pneumonia (1 paper, 2018). An acute, acute and chronic, or chronic inflammation focally or diffusely affecting the lung parenchyma, caused by an infection in one or both of the lungs (by bacteria, viruses, fungi, or mycoplasma.). "CAP2 cases and CAP1 controls were matched for age ± 4 years, sex, and Pneumonia Severity Index (PSI) score ± 10 points." (PMID 30263884, 2018).
psychosis (1 paper, 2020). "The significant group difference seen between BS and UHR in terms of CAP2 duration may relate to the neurodevelopmental etiology of psychosis, as basic symptoms are presumed to characterize the early, and UHR, the late, prodromal phase." (PMID 32116776, 2020).
sarcopenia (1 paper, 2023). Progressive decline in muscle mass due to aging which results in decreased functional capacity of muscles. "Moreover, the relevance of CAP2 in controlling heart and skeletal muscle function has been observed in CAP2 knockout mouse and confirmed by several human genetic studies, suggesting that CAP2 can be associated to sarcopenia, the biological substrate of physical frailty." (PMID 37537790, 2023).
Sinus bradycardia (1 paper, 2015). Bradycardia related to a mean resting sinus rate of less than 50 beats per minute. "For these studies we monitored six (4 cardiomyocyte-specific CAP2-null and 2 control) animals using ECG telemetry and found that all 4 cardiomyocyte-specific CAP2-null mice first developed sinus bradycardia and then died a few days later from complete atrioventricular block." (PMID 26616005, 2015).
Supraventricular tachycardia (1 paper, 2021). Supraventricular tachycardia (SVT) is an abnormally increased heart rate (over 100 beats per minute at rest) with origin above the level of the ventricles. "A deleterious mutation in the CAP2 gene of human patients also leads to supraventricular tachycardia and severe DCM23." (PMID 33742108, 2021).
Tremor (1 paper, 2024). An unintentional, oscillating to-and-fro muscle movement about a joint axis. "When the expression of CAP2 is reduced in PD, synaptic plasticity, brain function and motor function will be affected, and related symptoms such as cognitive dysfunction and tremor will appear." (PMID 38846945, 2024).
uterine cancer (1 paper, 2017). Primary or metastatic malignant neoplasm involving the uterine corpus and/or the cervix. "The evidence of CAP2 mutation was most predominant in uterine cancer." (PMID 28423713, 2017).
tumor (13 papers, 2016 to 2026). "JUN can cause the migration and infiltration of tumor cells, consistent with the function of CAP2 in GC cells." (PMID 37707957, 2023). "In this study, we evaluated the expression and function of CAP2 in GC and elucidated the mechanisms underlying the role of the CAP2-mediated interaction between tumor cells and macrophages in promoting GC metastasis." (PMID 37707957, 2023). "Our data suggest that CAP2, a key molecule mediating the interaction between GC cells and tumor-associated macrophages, may be a promising therapeutic target for suppressing tumor metastasis in GC." (PMID 37707957, 2023). "High CAP2 expression was significantly associated with advanced tumor grade." (PMID 32042970, 2020). "We proposed that CAP2 might be implicated in tumor progression by facilitating intracellular transport, proliferation, cell migration, and invasion, as shown in other tumors." (PMID 32042970, 2020). "Interestingly, S100A4, a protein recently found to be produced by LECs and to promote sprouting during tumor-associated lymphangiogenesis, emerged as one of the most strongly upregulated genes in the skin in both the cap1 and cap2 subsets and also in valve LECs." (PMID 41186588, 2026). "However, CAP2 expression was significantly associated with tumor grades (P = 0.014)." (PMID 32042970, 2020). "More CD163+ cells were found in high CAP2 expression tumor tissues, while there were more iNOS+ cells in low CAP2 expression tumor tissues, suggesting that CAP2 promotes M2 polarization but does not affect the chemotaxis of macrophages." (PMID 37707957, 2023). "Statistical analysis was also performed to assess CAP2 expression level in normal and tumor tissues, and to evaluate its clinicopathological and prognostic significance." (PMID 32042970, 2020). "In our study, CAP2 was obviously found in the cytoplasm and cell membranes among normal neurons and glial cells and tumor cells." (PMID 32042970, 2020). "It indicated that the tumor grade (HR, 2.733; CI 1.208–6.181; P = 0.016), CAP2 expression (HR, 1.843; CI, 1.252–2.714; P = 0.002) and Ki67 expression (HR; 1.016; CI, 1.00–1.031; P = 0.044) were independent prognostic variables for patients' overall survival." (PMID 32042970, 2020). "We also found that CAP2 was mainly located at the cell membrane and in the cytoplasm of tumor cells." (PMID 32042970, 2020). "The recurrent tumor was excised and the cells plated in vitro to test for the possible development of CAP2 resistance." (PMID 27973612, 2016). "In vitro, treatment of tumor-derived cells with CAP2 resulted in a concentration-dependent repression of TCF targets below the levels of DMSO-treated control cells, indicating the absence of drug resistance." (PMID 27973612, 2016). "Notably, the knockdown of CAP2 with 2′-O-methylation–modified RNA interference significantly reduced tumor lung metastasis." (PMID 37707957, 2023). "To determine whether CAP2 regulates GC in vivo, we injected GC cells transfected with lentiviral vector–shRNA–CAP2 (LV-shRNA-CAP2) or LV-shRNA-negative control (LV-shRNA-NC) into the tail vein of nude mice to observe tumor metastasis." (PMID 37707957, 2023). "Analysis of the association between CAP2 expression and clinicopathological parameters demonstrated that high CAP2 expression was positively correlated with clinical stage, distant metastasis, LNM, and tumor-node-metastasis (TNM) grade." (PMID 37707957, 2023). "Together, these data provide a better understanding of the mechanisms of tumor-macrophage interaction, and targeting CAP2 could provide new ideas for the treatment of GC metastasis." (PMID 37707957, 2023). "Moreover, Cox proportional hazard regression model was constructed including gender, tumor grade CAP2 expression and Ki67 expression." (PMID 32042970, 2020). "In addition, Spearman's rho correlation coefficient revealed a positive correlation between tumor grades and CAP2 expression (r = 0.427, P < 0.01)." (PMID 32042970, 2020).
tumor (continued). "This consistent difference in the levels of several WNT-TCF targets raised the possibility that whereas tumor recurrence might be due to incomplete dosage, the recurring tumor harbored the memory of previous CAP2 treatments." (PMID 27973612, 2016). "After 90 days following drug removal only one tumor re-grew, suggesting a penetrant effect of CAP2." (PMID 27973612, 2016). "Based on the gene expression data retrieved from the TCGA database, 4 of the 20 DEmRNAs (CAP2, CDKN3, MELK and UBE2T) were upregulated in tumor tissues, and the remaining DEmRNAs were upregulated in adjacent normal tissues." (PMID 33879119, 2021). "Detailed investigation of these Cap2 alterations and their functional consequences could reveal how CMTR2 influences tumor progression and immune responses." (PMID 41198678, 2025). "Furthermore, the majority of PDACs in the NAT‐group were classified as CAP‐2 (55%) and CAP‐3 (41%), indicating that tumor regression, the desired response to NAT, was either partial (CAP‐2) or poor/absent (CAP‐3)." (PMID 36400567, 2023). "In addition to that several molecular markers of tumor progression like HSP70, CAP2, GPC3, and GS were also expressed in expression profiling." (PMID 36479247, 2022). "Systemic delivery of CAP2, but not cyclodextrin carrier alone, resulted in the blockade of tumor growth without visible side effects in two independent experiments." (PMID 27973612, 2016). "In addition, multiple regression model was used without entering tumor grade variable since we already proved that tumor grade was correlated with CAP2 expression (Part 3.3)." (PMID 32042970, 2020).